IL1B (interleukin 1 beta)
Diseases named in the same sentence as IL1B in open-access papers (continued):
Sharing a sentence is not in itself a finding about the gene and the disease.
dry eye (80 papers, 2009 to 2025). "Increased transcriptional activity of FOS, JUN and ELK have been previously linked to activation of IL1b signaling, further implicating this pathway as a key driver of keratocyte inflammation in dry eye." (PMID 39677756, 2024). "Inflammation caused by postoperative dry eyes can increase the levels of inflammatory cytokines in tears, such as IL − 1a and IL-1b, TNF-a, IL-6, and IL-8, several of which play key roles in epithelial hyperproliferation and keratinization." (PMID 38259844, 2023). "Clinical studies reported that tears of dry-eye patients had increased levels of interleukin-1 alpha (IL-1α) and interleukin-1 beta (IL-1β), which were associated with corneal fluorescein staining." (PMID 34876936, 2021). "Significant increase in the infiltration of inflammatory cells on the ocular surface and the release of tumor necrosis factor-α (TNF-α), interleukin-1β (IL-1β), and so on was found in the patients with dry eye." (PMID 39403388, 2024). "Similar trends in NLRP3 gene expression and IL-1β levels were observed in patients with dry eye syndrome." (PMID 38533385, 2024). "Studies in animal models demonstrated that LPS up-regulates the expression of IL-12a, IL-1β, and IFN-γ in dry eye, as well as increasing the production of chemokines associated with Th1 cells, ultimately leading to Th1-related dry eye development." (PMID 38898418, 2024). "The presence and extent of corneal damage can reflect the severity of dry eye, while elevated inflammatory factors such as IL-1β and TNF-α indicate increased ocular inflammation." (PMID 39403388, 2024). "TNFα and IL-1β were previously used inflammatory inducers in preclinical studies, including in vitro dry eye models." (PMID 36675083, 2023). "Dry eye is accompanied by inflammation with increased levels of inflammatory and T cell-related mediators such as IL-1β, IL-6, TNF-α, IL-17, and IFN-γ, noted in the conjunctiva and tear fluid of dry eye patients." (PMID 36830827, 2023). "The mRNA expression of miR-146a, TNF-α, IL-1β, IL-6 and IL-8 in the corneas of dry eye model mice was measured by real-time quantitative PCR (RT-qPCR)." (PMID 37433841, 2023). "Zheng and colleagues found NLRP3, caspase-1, and IL-1b increased in impression cytology samples from patients with dry eye, as well as in cultured cells exposed to hyperosmolar medium." (PMID 36902183, 2023). "IL-1β has multiple activities in dry eye including stimulating expression of other innate cytokines and chemokines, matrix metalloproteinase-9 (MMP-9) a protease that disrupts corneal barrier function, and IL-17 production by γδT cells." (PMID 37036417, 2023). "Immunofluorescent staining results also indicated an increase in inflammatory cytokines such as IL-1β, IL-6, and TNFα in the dry eye group, while the dry eye + LED group exhibited an overall significant decrease." (PMID 38139321, 2023). "Increased IL-1β level was observed in tear film, conjunctiva, and aqueous humour of glaucoma patients but also in patients with dry eye syndrome and Meibomian gland dysfunction, frequent in patients on antiglaucoma medical treatment." (PMID 37770514, 2023). "In terms of the dry eye–related expression of inflammatory factors, the levels of IL-1β and IL-6 were assessed using qRT-PCR." (PMID 35185587, 2022). "It has been shown that dry eye-related inflammatory mediators (TNFα, IL-1β, IL6/IL17, and prostaglandin E2) upregulate MUC5AC mRNA expression." (PMID 36209216, 2022). "In the dry eye model proposed, an increased secretion of IL-1β was observed, as well as an upregulation of NF-κB, occludin and galectin-3 mRNA expression." (PMID 35562958, 2022). "Kaempferol can promote tear production and corneal repair by inhibiting proinflammatory factors such as IL-1B, IL-6, IL-8, and TNFα and has significant therapeutic effects in rabbit dry eye models." (PMID 36590763, 2022).
dry eye (continued). "Previous studies have shown that innate immune system-mediated inflammation occurs in dry eye, leading to the expression of proinflammatory cytokines, including IL-1β and IL-6, on the ocular surface." (PMID 36013601, 2022). "qPCR analysis revealed that the mRNA levels of TNF-α, IL-1β, and IL-6 in dry eyes were significantly up-regulated by 3.0, 2.6, and 3.3-fold, respectively, compared to the NS mice." (PMID 34445121, 2021). "In cornea and conjunctiva of normal or dry eye model mice, the mRNA expression levels of IL-1β, IL-6, IL-8, TNF-α, IFN-γ, and MMP-9 were investigated by real-time PCR in the presence or absence of isorhamnetin." (PMID 33921231, 2021). "qRT–PCR revealed increased inflammatory IL-1β, IL-6, IL-8 expression at 24 h following the induction of dry-eye and 24 h treatment with 100 μL sodium hyaluronate 0.15% (SH) in comparison with the control corneal tissue (p < 0.001; Student’s t-test)." (PMID 34959420, 2021). "A study in patients with thyroid orbitopathy (TO) related dry eye, demonstrated increased levels of conjunctival cytokines IL-1α, IL-1β and IL-6 in IC samples using immunofluorescence." (PMID 30673862, 2019). "Clinical studies have reported that tears of dry eye patients show increased levels of IL-1α and mature IL-1β which correlated to corneal fluorescein staining." (PMID 30673862, 2019). "Dry eye patients were found with higher levels of proinflammatory cytokines such as IL1α along with IL-1β, IL-6, IL-8, and tumor necrosis factor (TNF-α) in the tear film compared to normal controls." (PMID 30519584, 2018). "In the dry eye group, the initial concentrations of IL-1β, IL-6, IL-8, MCP-1, TNF-α and IFN-γ were 57.78 ± 5.25, 214.73 ± 18.17, 500.30 ± 38.69, 1518.42 ± 143.29, 385.11 ± 21.95, and 96.55 ± 8.19 pg/ml, respectively." (PMID 27695117, 2016). "Higher levels of inflammasome can in turn activate caspase-1 and the secretion of IL-1β and IL-18, which then induce the inflammatory damage of dry eye." (PMID 25962072, 2015). "The current study confirmed a significant increase in IL-1β and IL-18 mRNA and protein expressions in tears and on the ocular surface of dry eyes." (PMID 25962072, 2015). "We have previously shown increased expression of the pro-inflammatory cytokines TNF-α and IL-1β in ocular surface epithelia of the BTX-B lacrimal gland-injected dry eye mouse model." (PMID 22815633, 2012). "The importance of IL-1β in the etiology of corneal inflammatory disease such as dry eye and keratitis has been demonstrated in multiple cell types." (PMID 21364905, 2011). "Proinflammatory cytokines interleukin-1α (IL-1α), and interleukin-1β (IL-1β) have been detected in human conjunctival epithelium and tear film in dry eye." (PMID 19190733, 2009). "TNF-α, IL-1β, and IL-6 are major markers of ocular surface inflammation in dry eye." (PMID 38399289, 2024). "Importantly, antibodies to IL-17A, IL-23, and IL-1β conjugated to the agglutinin reduces manifestations of dry eye, even when applied just once daily." (PMID 37130912, 2023). "The dry eye signs, such as tear loss or inflammatory response, can be aggravated by NLRP12/NLRC4 inflammasome activation mediated GSDMD cleavage together with IL-33 and IL-1β." (PMID 36614174, 2023). "In addition, ROS has been reported to activate the NLRP3 inflammasome in environment-induced dry eye syndrome and conjunctivitis, and a significant increase in inflammatory factors, such as IL-1β, was observed." (PMID 33663554, 2021). "The fact that VEGF induces pro-inflammatory cytokines may explain why bevacizumab 0.05% eye drops can improve OSDI scores in dry eye patients, i.e., by inhibiting VEGF-A, itself, and other pain-associated cytokines, including IL-1β, IL-17 and IL-18." (PMID 32502179, 2020). "A recent study reported that reactive oxygen species could trigger NLRP3 inflammasome and lead to caspase-1 auto-activation and maturation of proinflammatory cytokines IL-1β in dry eye murine models." (PMID 25962072, 2015).
dry eye (continued). "Inflammation is also an important component of dry eye and polymorphisms in the proinflammatory cytokine genes IL-1β (SNP rs1143634) and IL-6R (SNP rs8192284) have been reported to associate with non-Sjogren dry eye symptoms in a Korean population." (PMID 25896684, 2015). "Increased levels of IL-1β at the ocular surface contributes to the epithelial damage observed in dry eye and also infectious eye diseases with an inflammatory component by inducing expression of other pro-inflammatory cytokines in corneal epithelial cells and other ocular cells." (PMID 21364905, 2011). "Clinical studies on dry eye patients reported an increase in pro-inflammatory cytokines and chemokines in tears and conjunctival cells such as interleukin (IL) -6, IL-8, TNF-α and IL-1β; a loss in conjunctival goblet cells; and an increase in immune activation and infiltration in the conjunctiva." (PMID 27486749, 2016). "Both IL-1β and IL-6 are proinflammatory cytokines that are secreted on the ocular surface in response to various pathologic stimuli, such as benzalkonium chloride-induced dry eye, desiccating stress induced dry eye, and microbial infections, such as P. aeruginosa, O. volvulus, or HSV-1." (PMID 27517861, 2016). "The RT-qPCR experiments demonstrated that the MSC-CM + Tβ4 treated group attenuated the expression of IL1β and TNF-α in the context of dry eye." (PMID 39837870, 2025). "A study showed lowered levels of IL-1β, IL-6, and TNF-α in dry eye participants after treatment with topical cyclosporine tds." (PMID 40565378, 2025). "In a murine model of dry eye, these nanocomplexes significantly reduced inflammatory markers, including TNF-α, ICAM-1, VCAM-1, MMP-2, MMP-9, IL-17, IL-1β, and IL-6, thereby underscoring their therapeutic utility in DED." (PMID 41300436, 2025). "For example, increases in the concentrations of inflammatory cytokines, such as IL-1B, Il-6, IL-8, and tumor necrosis factor-α (TNF-α), in tears are correlated with clinical indices of dry eye." (PMID 39596346, 2024). "In a mouse model for dry eye, increases in ROS production triggered NLRP3 inflammasome formation and activation, leading to the increased secretion of bioactive IL-1β." (PMID 37371417, 2023). "A desiccating stress-induced dry eye mouse model with elevated levels of NLRP3 inflammasome, ASC, and CASP1 has been detected together with mature IL-1β and IL-18." (PMID 36614174, 2023). "Remarkably, we found that the levels of IL-6, IL-1β, and TNF-α increased in the corneas of dry eyes but significantly decreased after multi-wavelength LED treatment; these cytokines thus contribute to dry eye inflammation." (PMID 38139321, 2023). "Similar to the effects seen with DOPG, topical doxycycline in mouse models of dry eye reduces expression of IL-1α, IL-1β, and TNF-α, and in LPS-stimulated corneal epithelial cells, it has been shown to reduce IL-1β transcription and translation." (PMID 36982926, 2023). "IL-6, IL-1β, and TNF-α play important roles in ocular inflammation; dry eye increases the levels thereof." (PMID 38139321, 2023). "The dry eye marker MMP-9, cytokines (IL-1β, IL-8), and pain markers (NGF, CGRP) were quantified in tear samples with immunoassays." (PMID 35886858, 2022). "For instance, in dry eye syndrome, this approach can inhibit inflammatory cytokines such as TNF-α and Il-1β." (PMID 35943663, 2022). "Once the NF-κB signaling pathway is inhibited, the expression of IL-1β, TNF-α, and IL-6 on the ocular surface of dry eye, as well as the activation of immune cells, can be down-regulated." (PMID 35812407, 2022). "The phosphorylation of NF-KB was reduced along with a decrease in TNF-α, IL-1β, and IL-6 in BAC-induced dry eye mice following treatment with KIOM-2015E." (PMID 36499298, 2022). "The expression of inflammatory factors such as IL-1β, IL-6, IL-8, TNF-a and IFN-γ and infiltrated inflammatory cells, has been shown to be increased on the ocular surface of dry eye patients." (PMID 35812407, 2022).
dry eye (continued). "In vitro studies have demonstrated that atorvastatin downregulates T helper cells and thereby decreases inflammatory cytokines such as IL-1β, IL-6, IL-17 and IFN-γ, which are elevated in blepharitis and dry eye patients." (PMID 35372440, 2022). "Previous clinical studies on inflammatory mediators that occur in dry eye disease have shown elevated levels of IL-1β, IL-8, and TNF-α in the tear film of dry eye patients." (PMID 33921231, 2021). "Increase in IL-1β and TNF-α levels in the basal epithelium of diabetic patients with dry eye has been reported." (PMID 32437405, 2020). "α-MSH at different doses decreased the transcript levels of TNF-α and IL-1β, and increased the levels of IFN-γ in the corneas and conjunctivas of the dry eye rats, suggesting an improvement on the microenvironment on ocular surface by this peptide." (PMID 26685899, 2015). "In the current study, we found that mRNA and protein expressions of NLRP3 inflammasome were upregulated in human dry eyes, especially in SSDE; the downstream inflammatory factors caspase-1, IL-1β, and IL-18 were also elevated in dry eye patients." (PMID 25962072, 2015). "α-MSH at both 10−3 and 10−4 mg/ml significantly reduced TNF-α and IL-1β expression, as compared to the saline- and 10−5 mg/ml α-MSH-treated dry eye corneas and conjunctivas." (PMID 26685899, 2015). "The results showed that α-MSH at different doses ameliorated tear secretion, tear film stability, and corneal integrity, and corrected overexpression of proinflammatory factors, TNF-α, IL-1β, and IFN-γ, in ocular surface of the dry eye rats." (PMID 26685899, 2015). "Our present study provides convincing evidence that conjunctival explants produced proinflammatory mediators such as IL-1β, TNF-α and MMP-9 in response to air exposure for about 1 week, resembling in vivo dry eye pathophysiology." (PMID 24498087, 2014). "In our previous reports using the botulinum toxin B-induced murine dry eye model, TNF-α and IL-1β were increased on both the ocular surface and lacrimal gland, whereas MIF was increased only in the lacrimal gland." (PMID 21152395, 2010). "Given that proinflammatory cytokines such as IL-1β, IL-6, IL-8, IL-10, interferon-γ (IFN-γ), and tumor necrosis factor-α (TNF-α) are elevated in dry eye patients under hyperosmotic conditions, curcumin emerges as a promising alternative therapeutic agent for DED." (PMID 41300436, 2025). "Furthermore, the mRNA expression of tumor necrosis factor-α (TNF-α), interleukin-6 (IL-6), and IL-1β in HCECs is inhibited by RGD-Alg@MSCs, which indicated a strong anti-inflammatory effect, crucial for mitigating dry eye symptoms." (PMID 40991713, 2025). "The findings in this study are consistent with those in our previous studies using the DS dry eye model that show levels of IL-18 and IL-1β transcripts do not significantly change over 10 days of DS." (PMID 37036417, 2023). "The expression levels of TNF-α and IL-1β in the DE-group were obviously higher than those in the C-group, indicating that TNF-α and IL-1β expression was induced during corneal inflammation in dry eye model mice." (PMID 37433841, 2023). "In addition to MMP-9, we also analyzed the level of the cytokines IL-1β and IL-8 after Femto-LASIK, which are also known to be elevated in dry eye." (PMID 35886858, 2022). "The activated kinases initiate a cascade of protein phosphorylation involving multiple kinases and activate nuclear transcription factors, such as NF-KB, e.g., that the expression levels of TNF-α, IL-1β, and IL-6 were downregulated in BAC-induced dry eye after treatment with KIOM-2015E." (PMID 36499298, 2022). "For example, in dry eye mouse models, bacterial lipopolysaccharides (LPS) increases the expression of inflammatory mediators including IL-1β, IL-6, CXCL10, IL-12a, and IFN-γ in the conjunctiva and IL-1β and CXCL10 in the cornea." (PMID 38983562, 2022).
dry eye (continued). "Likewise, the beneficial role of this carotenoid in dry eye treatment was confirmed in human corneal epithelial cells via reduction in TNF-α and IL-1β levels." (PMID 34677429, 2021). "On the other hand, ATX has been shown to have anti-inflammatory effects in a mouse model of hyperosmoticity-induced dry eye due to suppression of TNF-α and IL-1β, as well as down-regulation of high-mobility group box 1, a proinflammatory marker involved in ocular damage." (PMID 34677429, 2021). "In addition, isorhamnetin significantly reduced ocular surface damage and expression of interleukin (IL)-1β, IL-8, and tumor necrosis factor (TNF)-α in an experimental mouse model of dry eye." (PMID 33921231, 2021). "Particularly, treatment with ALA in cultures of corneal epithelial cells and when it is topically applied to a dry eye animal model has anti-inflammatory activity, decreasing the release and expression of inflammatory factors (TNF-a, IL-6, IL-1β, and IL-8) regulated by the NF-κB pathway." (PMID 31137826, 2019). "In the no dry eye group, the initial concentrations of IL-1β, IL-6, IL-8, MCP-1, TNF-α and IFN-γ were 2.11 ± 0.14, 13.36 ± 1.97, 143.83 ± 11.92, 55.49 ± 5.94, 9.04 ± 0.01 and 0.55 ± 0.19pg/ml, respectively." (PMID 27695117, 2016). "Dry eye also induces the secretion of cytokines such as IL6, IL-1β, TNF-α, and IFN-γ." (PMID 27555966, 2016). "Indeed, animals with dry eye receiving CCR2 antagonist presented a decrease in corneal alterations and in pro-inflammatory cytokines TNF-α and IL-1β on the ocular surface, confirming the importance of CCL2 in the pathology." (PMID 27486749, 2016). "In the no dry eye group, 1 day postoperative concentration of IL-1β, IL-6, IL-8, MCP-1, TNF-α and IFN-γ were 51.42 ± 6.05, 119.51 ± 12.19, 443.92 ± 34.51, 2128.74 ± 215.64, 159.73 ± 12.98, and 51.54 ± 6.82 pg/ml, respectively." (PMID 27695117, 2016). "In summary, based on tear samples and conjunctival impression cytology specimens of dry eye patients, we found that the expressions of NLRP3 inflammasome and its downstream inflammatory factors-caspase-1, IL-1β and IL-18 are upregulated in dry eye patients, especially in SSDE." (PMID 25962072, 2015). "The quantitative RT-PCR (qPCR) results showed the significant up-regulation in TNF-α, IL-1β, and IFN-γ mRNA levels in the saline-treated dry eye rats, as compared to the saline controls (D+NaCl vs NaCl+NaCl, p < 0.001 for TNF-α, p < 0.05 for IL-1β, p < 0.01 for IFN-γ)." (PMID 26685899, 2015). "It is suggested that rs1143634 of IL1B and rs8192284 of IL6R act as susceptibility variations in Korean non-Sjogren dry eye patients." (PMID 22128229, 2011). "This is in agreement with previous studies in symptomatic, moderate dry eye patients, where there were no increases in levels of IL-1β, IL-6, IL-8/CXCL8, GRO-b, ICAM-1, TRAIL, or ephrin A5 in tear fluid." (PMID 20508732, 2010). "The non-SS dry eye group showed significant changes in IL-1b, IL-10, and TNF-a, but not IL-8." (PMID 39408709, 2024). "Previous studies have shown that mRNA expression levels of interleukin (IL)-1β, IL-6, IL-8, tumor necrosis factor (TNF)-α, interferon (IFN)-γ, and matrix metallopeptidase (MMP)-9 were significantly increased in tears and conjunctiva of dry eye patients compared to normal controls." (PMID 33921231, 2021). "Indeed, our results in this study demonstrated that α-MSH at different doses rectified the overexpression of the proinflammatory genes, TNF-α, IL-1β, and IFN-γ in the scopolamine-induced dry eye corneas and conjunctivas, suggesting the potent anti-inflammatory effects of this peptide." (PMID 26685899, 2015). "In another study in which IL-1β, IL-6, and pro-matrix metalloproteinase (MMP)-9 tear levels were measured in patients with different types of ocular diseases, including a group of 20 hyposecretive moderate dry eye patients, only proMMP9 was significantly increased in DED patients." (PMID 20508732, 2010).